KREMEN2 (kringle containing transmembrane protein 2)
Description:
Receptor for Dickkopf proteins. Cooperates with DKK1/2 to inhibit Wnt/beta-catenin signaling by promoting the endocytosis of Wnt receptors LRP5 and LRP6. Plays a role in limb development; attenuates Wnt signaling in the developing limb to allow normal limb patterning and can also negatively regulate bone formation.
Synonyms: KRM2; MGC10791
Tractability: Antibody: its Gene Ontology location is reachable by antibodies, with high confidence; UniProt predicts a signal peptide or a membrane-spanning region.
Gene: Protein-coding gene on chromosome 16 (2,963,960 to 2,968,380, forward strand). Ensembl gene ENSG00000131650.
Subcellular location: Membrane
Pathways (Reactome):
Signal Transduction: Negative regulation of TCF-dependent signaling by WNT ligand antagonists; TCF dependent signaling in response to WNT
Disease: Signaling by LRP5 mutants
Gene Ontology:
Molecular function: transmembrane signaling receptor activity
Biological process: limb development; negative regulation of ossification; signal transduction; Wnt signaling pathway
Cellular component: early endosome membrane; plasma membrane; membrane
Genetic constraint (gnomAD): Loss-of-function variants: 43 observed, 39.66 expected, observed/expected ratio (o/e) 1.08, 90% interval 0.85 to 1.4. The synonymous counts are far from expectation, so gnomAD's model fits this gene poorly and the ratio says little. Missense variants: 686 observed, 526.92 expected, observed/expected ratio (o/e) 1.3, 90% interval 1.22 to 1.39. Synonymous variants: 355 observed, 242.42 expected, observed/expected ratio (o/e) 1.46, 90% interval 1.34 to 1.6.
Homologues: Orthologues: chimpanzee KREMEN2 (99% identical), macaque KREMEN2 (97% identical), pig KREMEN2 (90% identical), rat Kremen2 (88% identical), mouse Kremen2 (87% identical), guinea pig KREMEN2 (85% identical), dog KREMEN2 (76% identical), tropical clawed frog kremen2 (44% identical). Paralogues in human: KREMEN1 (37% identical).
Diseases named in the same sentence as KREMEN2 in open-access papers:
KREMEN2 is named in the same sentence as 28 diseases in open-access papers, as found by Europe PMC text mining. Sharing a sentence is not in itself a finding about the gene and the disease. The quoted sentences say what the papers report.
gastric cancer (4 papers, 2020 to 2024). A primary or metastatic malignant neoplasm involving the stomach. "In addition, studies showed that the increased expression of KREMEN2 appeared to promote tumorigenesis and metastasis in gastric cancer and was associated with a worse prognosis in colon cancer." (PMID 39201553, 2024). "In addition, Kremen2 expression is positively associated with the development of gastric cancer." (PMID 37270563, 2023). "The transmembrane receptor Kremen2 has been reported to participate in the tumorigenesis and metastasis of gastric cancer." (PMID 37270563, 2023). "Furthermore, phosphorylation of PI3K (Y607) and AKT (Ser473) was significantly downregulated after Kremen2 knockdown in H1703 cells, which was consistent with the results from a study on Kremen2 in gastric cancer." (PMID 37270563, 2023). "The proliferation of gastric cancer cells was considerably inhibited after knocking down Kremen2, indicating that Kremen2 may exert oncogene-like functions, thus promoting gastric cancer proliferation." (PMID 37123533, 2023). "Relationship between Kremen2 expression and tumor characteristics in patients with gastric cancer." (PMID 33489867, 2020).
osteoporosis (4 papers, 2010 to 2024). A condition of reduced bone mass, with decreased cortical thickness and a decrease in the number and size of the trabeculae of cancellous bone (but normal chemical composition), resulting in increased fracture incidence. "Here we show that Kremen-2 (Krm2) is predominantly expressed in bone, and that its osteoblast-specific over-expression in transgenic mice (Col1a1-Krm2) results in severe osteoporosis." (PMID 20436912, 2010). "Furthermore, overexpression of Kremen2 in mice resulted in severe osteoporosis with decreased osteoblast and increased osteoclast differentiation and function." (PMID 39201553, 2024).
breast invasive carcinoma (2 papers, 2020 to 2023). "Recent research reveals that Kremen2 is upregulated in various tumours, such as renal clear cell carcinoma, breast invasive carcinoma, COAD, and stomach adenocarcinoma, in comparison to that in normal tissues." (PMID 37123533, 2023).
colon cancer (2 papers, 2023 to 2024). "Even though Kremen2 serves as a prognostic indicator in individuals with malignant tumours, its role in evaluating the prognosis of individuals with colon cancer has not been confirmed." (PMID 37123533, 2023).
lung carcinoma (2 papers, 2023 to 2025). "In addition to their role in embryonic development, Wnt and SOX interactions are associated with many types of cancer; interestingly, Kremen2 has also been reported to be involved in gastric, colon and lung cancers." (PMID 41214364, 2025). "Furthermore, Kremen2 is highly expressed in a variety of tumors, particularly in squamous lung cancer, but the expression of Kremen1 is absent in 30 different human tumor cell lines, especially in the human lung cancer cell lines (Lu99, EBC1, SBC2, and SBC5)." (PMID 37270563, 2023). "The analysis revealed significantly different Kremen2 expression, which has not been studied in lung cancer." (PMID 37270563, 2023). "In our experiments, knockdown of Kremen2 resulted in increased levels of p-LRP6 and LPR6 protein in H1703 cells while the levels of p-LRP6 and LPR6 did not change obviously in A549 cells, implying Kremen2 might play different roles in different lung cancer cells." (PMID 37270563, 2023).
non-small cell lung carcinoma (2 papers, 2023 to 2025). A group of at least three distinct histological types of lung cancer, including non-small cell squamous cell carcinoma, adenocarcinoma, and large cell carcinoma. "In non-small cell lung cancer, Kremen2 drives tumor progression by preventing SOCS3-mediated ubiquitination of EGFR." (PMID 40170095, 2025).
Alzheimer disease (1 paper, 2019). A progressive, neurodegenerative disease characterized by loss of function and death of nerve cells in several areas of the brain leading to loss of cognitive function such as memory and language. "Therefore, our results suggest that KREMEN2 could be proposed as a link between TG and Alzheimer’s disease and CAD through methylation profiles." (PMID 30813608, 2019).
kidney tumor (1 paper, 2024). "Moreover, we used a published data set (GSE11482) to confirm that expression of KREMEN2 mRNA in kidney rhabdoid tumors, which are deficient in the SMARCB1 gene, was significantly higher than that in other types of kidney tumor." (PMID 38839769, 2024).
lung squamous cell carcinoma (1 paper, 2023). "The results showed that Kremen2 expression was significantly upregulated in NSCLC tissues, particularly in lung squamous cell carcinoma (LUSC) tissues, compared with adjacent normal lung tissues (P < 0.05)." (PMID 37270563, 2023).
lymph node metastasis (1 paper, 2023). "In contrast with individuals with CC having no lymph node metastasis, individuals with CC having lymph node metastasis had substantially greater levels of Kremen2 protein expression (p = 0.036)." (PMID 37123533, 2023).
osteoarthritis (1 paper, 2022). A noninflammatory degenerative joint disease occurring chiefly in older persons, characterized by degeneration of the articular cartilage, hypertrophy of bone at the margins and changes in the synovial membrane. "For several polymorphisms in the IL1B locus, in the IL1RN VNTR and also RANK, KREMEN2 among others associations with osteoarthritis were described." (PMID 36518750, 2022).
cancer (11 papers, 2017 to 2025). A tumor composed of atypical neoplastic, often pleomorphic cells that invade other tissues. "In other words, increased expression of KREMEN2 in cancers deficient in the cBAF complex has antiapoptotic effects, and repression of KREMEN2 via inhibition of CBP/p300 is the determinant of synthetic lethality." (PMID 39625239, 2025). "KREMEN2 (cg07140290), encoding Kringle-Containing TransmembraneProtein 2, is a protein implicated in cancer immunosurveillance in relation to WNT signaling." (PMID 35189960, 2022). "Consistently, we found that KREMEN2 expression is increased in a large majority of cancers and that high KREMEN2 expression in tumors is linked to a poor outcome in multiple cancers." (PMID 31069116, 2019). "Furthermore, treatment with CBP/p300 dual inhibitor suppressed the growth of xenografts derived from SMARCA4/SMARCA2-deficient and SS18–SSX fusion cancer cells, resulting from repression of KREMEN2 and induction of apoptosis." (PMID 39625239, 2025). "Because SMARCA4/SMARCA2-deficient and SS18–SSX fusion cancer cells depend on transcriptional upregulation of KREMEN2 due to SMARCA4/SMARCA2 deficiency and SS18–SSX fusion, we clarified that synthetic lethality is induced by repressing expression of KREMEN2 by simultaneous inhibition of CBP/p300." (PMID 39625239, 2025). "Thus, SMARCA4/SMARCA2-deficient and SS18–SSX fusion cancer cells depend on the expression of KREMEN2." (PMID 39625239, 2025). "In addition, expression levels of KREMEN2 pre-mRNA in SMARCB1-deficient cell lines was higher than that in SMARCB1-proficient cell lines in the cancer cell line model." (PMID 38839769, 2024). "Thus, SMARCB1-deficient cancer cells are dependent on KREMEN2 expression." (PMID 38839769, 2024). "To further examine expression levels of the KREMEN2 gene among cell lines with different genetic abnormalities, we used mutation, copy number and gene expression data from the CCLE (Cancer Cell Line Encyclopedia) database in DepMap (data version 23Q2)." (PMID 38839769, 2024). "According to The Cancer Genome Atlas (TCGA) data, more than 65% of the tissue samples in 18 different types of cancer, revealed that Kremen2 expression in cancerous tissues was greater in comparison to that in paired normal tissues." (PMID 37123533, 2023). "First, previous studies on Kremen2 and the Wnt pathway were based on normal cells, and few studies have been performed on cancer cells, especially NSCLC." (PMID 37270563, 2023). "Early studies on Kremen2 focused on its effects on embryonic development and bone formation, while the important role of Kremen2 in cancers has been slowly discovered in recent years." (PMID 37270563, 2023). "Consistently, low KREMEN2 expression is a good prognostic for patient survival in a variety of cancers." (PMID 31069116, 2019). "In cBAF-deficient cancer cells, inhibition of CBP/p300 leads to marked repression of KREMEN2, which reduces cell viability; this suggests that expression of the KREMEN2 gene is induced cooperatively by CBP and p300 and that it is required for the viability of cBAF-deficient cells." (PMID 39625239, 2025). "To further confirm that KREMEN2 is a determinant of synthetic lethality through simultaneous inhibition of CBP/p300 in SMARCA4/SMARCA2-deficient cells and SS18–SSX fusion cancer cells, we investigated whether depleting KREMEN2 affects cell viability." (PMID 39625239, 2025). "Our clinical data show that Kremen2 expression was positively correlated with LUAD patient pathological grade, suggesting that Kremen2 may be involved in cancer metastasis." (PMID 37270563, 2023). "We found that KREMEN2 expression is increased in a large majority of cancers, suggesting it may confer increased survival capacity." (PMID 31069116, 2019). "Furthermore, in order to investigate epistasis between KREMEN1 and KREMEN2, we compared the influence of KREMEN2 expression on the survival of patients from all cancer cohorts ranked by the level of KREMEN1 expression in tumor." (PMID 31069116, 2019).
cancer (continued). "Furthermore, we proposed the following molecular mechanism underlying synthetic lethality induced by simultaneous inhibition of CBP/p300 in SMARCB1-deficient cancers: in SMARCB1-proficient cells, the SWI/SNF complex containing SMARCB1 represses transcription of KREMEN2." (PMID 39625239, 2025). "When considering only the cancer types in which KREMEN1 is upregulated, we found KREMEN2 to fall among the most significantly upregulated genes." (PMID 31069116, 2019). "Other genes, such as ALOXE3, HBQ1, KREMEN2, SYT13, DOK7, CDC5L, and FBXO6, have been reported in several cancers." (PMID 28404969, 2017). "Mechanistically, Kremen2 may exert its oncogenic effect by interacting with SOCS3 and blocking the ubiquitin-dependent EGFR degradation, thereby sustaining the EGFR-mediated cancer signaling pathways and promoting cell proliferation and metastasis of NSCLC." (PMID 37270563, 2023). "By contrast, KREMEN2 expression was found to be increased in tumor compared with normal tissue in >80% of samples considered, regardless of the cancer type." (PMID 31069116, 2019). "In addition, depletion of KREMEN2 reduced the viability of SMARCB1-deficient cell lines, but not that of SMARCB1-proficient cell lines, in the cancer cell line panel." (PMID 38839769, 2024).
tumor (10 papers, 2010 to 2025). "In summary, this research highlighted that Kremen2 expression was upregulated in CC tissues and was strongly linked to tumour progression and prognosis in individuals with CC." (PMID 37123533, 2023). "Clinical correlation analysis highlighted that a high level of Kremen2 expression was strongly linked with tumour progression, particularly lymph node metastasis." (PMID 37123533, 2023). "It is possible that Kremen2, as a suppressor of Kremen1, inhibits Kremen1-induced cell death and Kremen2 may promote the survival of tumor cells in a ligand-deficient environment." (PMID 37270563, 2023). "When we examined the relationship between clinicopathological parameters and Kremen2 mRNA expression in patients with CC based on TCGA, we observed that high Kremen2 mRNA expression was linked to tumour N stage (from N0 to N2 and from N1 to N2) (p = 0.005, 0.012)." (PMID 37123533, 2023). "The relatively higher Kremen2 expression in the advanced N stage indicated that it could be linked to tumour progression in CC." (PMID 37123533, 2023). "To address this issue, we examined the effect of Kremen2 on the metastatic ability of tumor cells in vitro and in vivo." (PMID 37270563, 2023). "Based on the TIMER data, we observed Kremen2 mRNA overexpression in various tumours, including CC (p < 0.001)." (PMID 37123533, 2023). "Currently, there is growing interest in studying the mechanism of Kremen2 in tumorigenesis and tumour development." (PMID 37123533, 2023). "We provide in vitro and in vivo evidence to support the tumor-promoting effect of Kremen2 in NSCLC progression and metastasis." (PMID 37270563, 2023). "Kremen2 was highly expressed in tumor tissues from NSCLC patients and was positively correlated with a poor patient prognosis." (PMID 37270563, 2023). "We analysed the ISs in 113 tumour tissues and 46 paired adjacent normal tissues to verify Kremen2 protein expression in CC." (PMID 37123533, 2023). "Consistent results were obtained from the A549 xenograft model, in which knocked down expression of Kremen2 substantially inhibited tumor size and tumor weight." (PMID 37270563, 2023). "Kremen2 involvement in the development of the embryo, bone, neural ridge, and tumours has been demonstrated by several studies." (PMID 37123533, 2023). "That study suggested that Kremen2 might be involved in tumor development by affecting the AKT transcriptional level." (PMID 37270563, 2023). "Subgroup analysis was performed based on the age, sex, tumour site, TNM stage, CEA, tumour size, differentiation, peripheral nerve invasion, lymphovascular invasion, and MMR for determining the association of Kremen2 protein expression and clinicopathological parameters." (PMID 37123533, 2023). "Additionally, the Kremen2 expression level was higher in tumor tissues after comparing the raw Kremen2 RNA-seq data for each pair of TCGA samples." (PMID 37270563, 2023). "A xenograft model of nude mice was generated by subcutaneously injecting A549 cells with stable Kremen2 knockdown to verify whether these in vitro findings were relevant to NSCLC tumor growth in vivo." (PMID 37270563, 2023). "IHC staining further showed that Kremen2 expression was high in tumor tissues." (PMID 37270563, 2023). "High expression of Kremen2 enhanced tumor cell growth and metastasis in NSCLC in vitro and in vivo." (PMID 37270563, 2023). "In B16F10 tumor sections, KREMEN2 was expressed in essentially all cell types, including ECs." (PMID 24091497, 2014). "To further understand whether Kremen2 promotes tumor metastasis in vivo, we performed a tail vein metastasis experiment with A549-Krm2KO cells and A549-Krm2KO + OE-Krm2 cells (A549-Krm2KO cells overexpressing Kremen2)." (PMID 37270563, 2023).
tumor (continued). "None is obviously expressed in this tumor, but the variants in both KREMEN2 and BANP are expressed in subsequent tumors with higher quality and higher-depth RNA-seq, so it is likely that these variants are expressed below our level of sensitivity in this resection sample." (PMID 29440180, 2018). "Their role is underscored by the accumulation of mutations in additional regulators of their activation during the course of this tumor's treatment: MAPK (SPRY3), PI3K (DEPDC5), and WNT (KREMEN2, NET1, GPR124)." (PMID 29440180, 2018). "Our results suggest that Kremen2 may prevent the EGFR degradation and play an important role in tumor progression and metastasis of NSCLC." (PMID 37270563, 2023).
KREMEN2 also shares sentences with these, for which no sentence is quoted: stomach adenocarcinoma (2 papers); -Deficient (1); amyotrophic lateral sclerosis (1); bone tumor (1); breast carcinoma (1); colon adenocarcinoma (1); fibromatosis (1); gingival hyperplasia (1); glioma (1); head and neck squamous cell carcinoma (1); hereditary gingival fibromatosis (1); Osteolysis (1); osteosclerosis (1); renal clear cell carcinoma (1); rhabdoid tumor (1).